ALB (albumin)
Diseases named in the same sentence as ALB in open-access papers (continued):
Sharing a sentence is not in itself a finding about the gene and the disease.
non-small cell lung carcinoma (continued). "Owing to its favorable clinical efficacy and safety profile, nanoparticle albumin-bound paclitaxel (nab-paclitaxel) has been approved by the U.S. Food and Drug Administration (FDA) for the treatment of metastatic breast cancer, non-small cell lung cancer (NSCLC), and other malignancies." (PMID 40958832, 2025). "Background and Objectives: This study aimed to investigate the prognostic value of the hemoglobin–albumin–lymphocyte–platelet (HALP) score—a marker reflecting both inflammatory and nutritional status—in patients with metastatic non-small cell lung cancer (NSCLC) undergoing immunotherapy." (PMID 40572677, 2025). "The CALLY Index, integrating albumin, lymphocyte count, and CRP, stands out as an emerging marker with demonstrated prognostic importance in several cancers like gastric, colorectal, and Non-Small Cell Lung Cancer (NSCLC)." (PMID 40034601, 2025). "The Scottish inflammatory prognostic score (SIPS), a novel and straightforward inflammatory score that combines albumin (ALB) and NEU, was recently proposed and has shown to be a more accurate predictor in non-small-cell lung cancer (NSCLC) patients receiving first-line ICIs." (PMID 39035002, 2024). "Drug delivery via nanoparticle-based carriers has shown promising pharmacological improvements in cancer therapy Nanoparticle albumin-bound paclitaxel (Abraxane) has been approved by FDA for use in patients with metastatic breast cancer and Non-small-cell lung carcinoma (NSCLC)." (PMID 26182353, 2015). "Lastly, cabazitaxel-loaded human serum albumin nanoparticles combined with transforming growth factor beta-1 siRNA lipid nanoparticles (CTX-HSA-NPs and TGFβ-1 siRNA LNP) were developed specifically for the treatment of paclitaxel-resistant non-small cell lung cancer." (PMID 38794306, 2024). "Abraxane is an albumin-bound, solvent-free paclitaxel NP manufactured by Abraxis BioScience that first received FDA approval in 2005 for breast cancer therapy, and then, in 2012, was approved in combination with carboplatin as a first-line therapy for advanced non-small-cell lung cancer (NSCLC)." (PMID 37214453, 2023). "In the non-small cell lung cancer set treated with chemoradiotherapy, a correlation was found for WBC, CRP, and albumin but not for hemoglobin, NLR, and PLR." (PMID 36354870, 2022). "In the set of non-small cell lung cancer treated with curative surgical resection, the authors found a positive correlation between the FDG uptake of bone marrow on PET/CT with serum CRP, NLR, and WBC count and a negative correlation with albumin level." (PMID 36354870, 2022).
diabetic retinopathy (98 papers, 2009 to 2026). "This study demonstrated that the CRP/albumin ratio is a significant inflammatory marker in diabetic retinopathy and is associated with disease progression." (PMID 40941666, 2025). "Even after adjusting for confounding factors such as sex, age, albumin, hemoglobin, and diabetic retinopathy, the association between pedal MAC and amputation remained significant (OR 2.29, 95% CI 1.33–3.93, p = .003)." (PMID 38584152, 2024). "Red blood cell distribution width/albumin ratio (RAR) has been reported as an independent risk factor for diabetic retinopathy (DR), while its association and predictive value in the prognosis of DR patients has not been reported." (PMID 38128055, 2023). "The multivariate logistic regression analysis revealed that high SUA, homocysteine, TC, LDL-c, and urinary albumin levels were associated with more serious diabetic retinopathy (OR > 1; P < 0.05)." (PMID 33256661, 2020). "In our study, we found that high urinary albumin levels were associated with more serious diabetic retinopathy (OR = 1.003; 95% CI = 1.049–1.198; P = 0.043)." (PMID 33256661, 2020). "In conclusion, we found that that high SUA, homocysteine, TC, LDL-c, and urinary albumin levels were associated with the severity of diabetic retinopathy." (PMID 33256661, 2020). "The associations of SUA, homocysteine, TC, LDL-c and urinary albumin levels with the severity of diabetic retinopathy were identified by using the multivariate logistic regression analysis." (PMID 33256661, 2020). "Albuminuria is closely associated with diabetic retinopathy (DR), but the precise role of the albumin-to-creatinine ratio (ACR) in screening for DR remains to be determined." (PMID 28924157, 2017). "Previous studies have suggested that decreased albumin levels may be associated with the development of diabetic retinopathy." (PMID 40151349, 2025). "Our findings not only enrich the current body of evidence but also suggest that maintaining optimal serum albumin levels could be a therapeutic target for mitigating the risk of diabetic retinopathy." (PMID 38369636, 2024). "Association between serum albumin (g/dl) and diabetic retinopathy status." (PMID 35709212, 2022). "The higher levels of systolic blood pressure, proteinuria, total cholesterol, LDL-C, HDL-C, advanced class of glomerular lesion, IFTA, interstitial inflammation, arteriolar hyalinosis, incidence of diabetic retinopathy, and the lower levels of serum albumin and eGFR were associated with ESKD." (PMID 34393995, 2021). "In most studies, the deleterious effects of glycated albumin have been highlighted for instance the physiopathological correlation between glycated albumin and diabetic renal deficiency and microangiopathy and also diabetic retinopathy." (PMID 24708663, 2014). "This study investigates the relationship between the albumin‐to‐creatinine ratio and diabetic retinopathy (DR) in US adults using NHANES data from 2009 to 2016." (PMID 39826101, 2025). "By mitigating vascular leakage and edema, serum albumin helps preserve the integrity of the vascular wall, thereby potentially preventing the onset and progression of diabetic retinopathy." (PMID 40151349, 2025). "This study investigates the relationship between albumin‐to‐creatinine ratio and diabetic retinopathy (DR) in US adults using NHANES data from 2009 to 2016." (PMID 39826101, 2025). "We evaluated the relationship between serum albumin (ALB) and diabetic retinopathy (DR) using logistic regression analysis after adjusting for potential confounders." (PMID 38369636, 2024). "According to diabetic retinopathy (DR) and urinary albumin-creatinine ratio (UACR), the 407 people were divided into four groups, DR(–)UACR(–), DR(+)UACR(–), DR(–)UACR(+), and DR( + )UACR(+)." (PMID 38987257, 2024). "Limited studies have focused on the relationship between diabetic retinopathy (DR) and the hemoglobin, albumin, lymphocyte, platelet (HALP) score." (PMID 38800491, 2024).
diabetic retinopathy (continued). "Most studies had shown a linear relationship between serum albumin (sALB) and the prevalence of diabetic retinopathy (DR)." (PMID 38429639, 2024). "The hemoglobin, albumin, lymphocyte, and platelet score (HALP), a new index reflecting the nutritional and inflammatory status, has been associated with a higher risk of diabetic retinopathy, particularly at lower values (≤ 42.9)." (PMID 38982136, 2024). "Patients with PAD and pedal MAC exhibited a significantly elevated risk of amputation (OR 3.64, 95% CI 1.91–6.95, p < .001) even after adjusting for sex, age, albumin, hemoglobin, and diabetic retinopathy status." (PMID 38584152, 2024). "Fundus photography and fluorescein angiography were performed to assess diabetic retinopathy, and estimated glomerular filtration rate and albumin-to-creatinine ratio were measured to evaluate renal function." (PMID 37779807, 2023). "Angiopoietin-2 showed positive significant correlation with albumin (p=0.008) and glycated albumin (p=0.005) in diabetic retinopathy group (Table-III)." (PMID 36415281, 2022). "The significant positive correlation of glycated albumin and angiopoietin-2 in individuals with diabetic retinopathy suggests an interrelated pathway in the genesis and progression of the disease." (PMID 36415281, 2022). "Predictors of DKD risk include albumin excretion rate (AER), blood pressure, blood glucose, glomerular filtration rate (GFR), diabetic retinopathy, and plasma lipid levels." (PMID 35346252, 2022). "Patients with glomerular C3 deposition had a higher prevalence of diabetic retinopathy, lower serum albumin level, lower serum C3 level, and more severe pathologic phenotype of DN than those without such deposition." (PMID 35711407, 2022). "Mean serum albumin in diabetic retinopathy and non-diabetic retinopathy group was 4.20 ±0.56 gm/dL and 4.43 ±0.39 gm/dL respectively (p=0.031)." (PMID 36415281, 2022). "Compared with patients who did not progress to ESRD, those who did had higher baseline proteinuria, prevalence of diabetic retinopathy, and prevalence of haematuria; and lower baseline eGFR, serum albumin concentration, and haemoglobin concentration." (PMID 33633132, 2021). "Primary Outcome: composite end-point of diabetic retinopathy estimated by the Early Treatment Diabetic Retinopathy Study Score, urinary albumin to creatinine ratio, and skin conductance in feet estimated by the sudomotor index." (PMID 32282852, 2020). "The patients with a degree of diabetic retinopathy greater than mild (moderate/severe/proliferative) presented with higher glycated hemoglobin, systolic blood pressure, triglycerides, and urinary albumin excretion and were more likely on insulin treatment." (PMID 27200379, 2016). "Patients with diabetic retinopathy had a significant higher insulin dose, disease duration, HbA1, urinary albumin/creatinine ratio and serum adiponectin." (PMID 27275296, 2015). "Clements used db/db mice to state that Anti-glycated albumin therapy offered prophylaxis against the early changes of diabetic retinopathy." (PMID 25411784, 2014). "As the UAER was a strong predictor of the presence for DR, we analyzed the prevalence of diabetic retinopathy according to the tertiles of urinary albumin excretion rate." (PMID 22747972, 2012). "Albumin, being the most prevalent serum protein produced by the liver, significantly contributes to minimizing oxidative stress and controlling inflammation—two critical factors in the development of diabetic retinopathy." (PMID 40234618, 2025). "In the subset of patients with PAD, pedal MAC remained significantly associated with an increased the risk of amputation in both crude model (OR 3.03, 95% CI 1.77–5.20, p < .001) and after adjusting for sex, age, albumin, hemoglobin, and diabetic retinopathy (OR 2.14, 95% CI 1.14–4.02, p = .018)." (PMID 38584152, 2024).
diabetic retinopathy (continued). "Pedal MAC showed a significant association with amputation both in unadjusted analysis (odds ratio [OR] = 2.98, 95% confidence interval [CI] = 1.86–4.76, p < .001) and after adjusting sex, age, albumin levels, hemoglobin levels, and diabetic retinopathy status (OR 2.29, 95% CI 1.33–3.93, p = .003)." (PMID 38584152, 2024). "Future studies could consider using a longitudinal cohort design to more accurately explore the relationship between serum albumin levels and diabetic retinopathy." (PMID 38369636, 2024). "According to univariate analysis, the reduced GLS exhibited association with the clinical features including HbA1c, triglyceride, systolic blood pressure, fasting glucose, heart rate, diabetic retinopathy, and urinary albumin creatinine ratio (UACR) (all p < .05)." (PMID 36959088, 2023). "The grade of diabetic retinopathy was correlated with albumin levels." (PMID 35155044, 2022). "In addition, it is well- known that patients with both a high albumin excretion rate (AER) and low glomerular filtration rate (GFR) at baseline will have the higher risk of diabetic retinopathy in type 2 diabetic patients." (PMID 36004355, 2022). "Univariate analyses revealed that bile acids, diabetic retinopathy (DR), body mass index (BMI), eGFR, hemoglobin, serum albumin, initial proteinuria, glomerular class, interstitial fibrosis, and tubular atrophy, and the use of RASI were risk factors for progression to ESRD (P < 0.05)." (PMID 36277729, 2022). "This study aims to investigate the albumin excretion rate in patients with diabetic retinopathy." (PMID 32509246, 2020). "Several studies have assessed the albumin excretion rate in diabetic retinopathy." (PMID 32509246, 2020). "Studies have shown that also normotensive subjects with a non-dipper BP profile have increased left ventricular mass and relative wall thickness, reduced myocardial diastolic function, increased urinary albumin excretion, increased prevalence of diabetic retinopathy, and impaired glucose tolerance." (PMID 31484988, 2020). "Additionally, we performed studies in a human vitreous sample obtained from a diabetic retinopathy patient to assess how the disease state may alter the FabA–albumin complexation profile." (PMID 32858986, 2020). "In conclusion, our research unveils a marked negative correlation between serum albumin levels and the presence of diabetic retinopathy among type 2 diabetic patients." (PMID 38369636, 2024). "On the other hand, the median height, blood Hb and Htc, serum albumin, C-reactive protein, HbA1c, and fasting glucose of the patients with and without diabetic retinopathy were significantly different (p < 0.05 for all)." (PMID 37762893, 2023). "This study reports that diabetic patients with diabetic retinopathy have higher levels of glycated albumin and angiopoitin-2 as compared to non-DR diabetics." (PMID 36415281, 2022). "The negative correlation between serum albumin and diabetic retinopathy was statistically meaningful within those three models." (PMID 35709212, 2022). "Ischemia modified albumin (IMA) may aid in the early detection and management of diabetic retinopathy (DR)." (PMID 35634607, 2022). "Diabetic retinopathy group had mean±SD 4.20 ±0.56 gm/dL while diabetic non-retinopathy group had mean±SD 4.43 ±0.39 gm/dL of albumin and significant difference was observed by Student “t” test (p=0.031; Table-II)." (PMID 36415281, 2022). "In diabetic retinopathy group, mean±SD percent glycated albumin (percent) was 30.71 ±18.63% and in diabetic non-retinopathy group, the median IQR was 11.80 (5.06-27.25)." (PMID 36415281, 2022). "In diabetic retinopathy group, mean glycated albumin (percent) was 30.71±18.63% and in non-diabetic retinopathy group, the median IQR was 11.80 (5.06-27.25) (p= 0.001)." (PMID 36415281, 2022). "In diabetic retinopathy group, mean±SD glycated albumin (gm/dl) was 1.26 ±0.76 and median IQR in diabetic non-retinopathy was 0.52 (0.23-1.10) respectively." (PMID 36415281, 2022).
diabetic retinopathy (continued). "In diabetic retinopathy group, mean glycated albumin was 1.48 (0.63-1.76) gm/dL and median IQR in non-diabetic retinopathy was 0.52 (0.23-1.10) gm/dL (p=0.003)." (PMID 36415281, 2022). "According to the results, there must have been a statistically significant negative relationship involving serum albumin and diabetic retinopathy in three categories of the regression model." (PMID 35709212, 2022). "In this study, we aim to quantify the relationship between diabetic retinopathy and urine albumin excretion and to correlate the urinary albumin excretion (normoalbuminuria, microalbuminuria, macroalbuminuria) with the severity and grade (mild, moderate, severe NPDR or PDR) of diabetic retinopathy." (PMID 35155044, 2022).
Arthritis (91 papers, 2004 to 2026). Inflammation of a joint. "The most influential features identified in our study, including oral ulcers, arthritis, anti‐DNA antibodies, and albumin, showed partial alignment with traditional diagnostic systems." (PMID 41583997, 2026). "With regard to experimental arthritis, it is interesting to note that the lack/blockade of CSF-1 as well as the blockade of CSF-1R is associated with less severe methylated bovine serum albumin (mBSA)-induced arthritis and CIA." (PMID 30886947, 2017). "The antirheumatic conpound methotrexate covalently linked to albumin has shown promising activity in the collagen-induced arthritis model." (PMID 23006786, 2012). "By identifying arthritis, oral ulcers, albumin, and anti‐DNA as key diagnostic indicators, the models provide valuable guidance for clinicians evaluating suspected BD cases, particularly in settings with limited access to rheumatology specialists or where clinical presentation is ambiguous." (PMID 41583997, 2026). "The inflammatory process during arthritis, observed in adult cases, can cause such a decrease in albumin levels, whereas the low levels of serum globulin in children could have been associated with the increased albumin to globulin ratio." (PMID 34339379, 2021). "In order to assess the impact of these key features, we repeat the experiment by testing the five models using the dataset containing only 36 features by eliminating the four identified features of arthritis, oral ulcers, albumin, and anti‐DNA." (PMID 41583997, 2026). "In XGBoost, the gain‐based embedded importance in XGBoost displayed a nearly identical pattern: arthritis held the top rank, with albumin and oral ulcers next, followed by PT and anti‐DNA." (PMID 41583997, 2026). "In the permutation analysis, permuting arthritis caused the largest decrease in ROC‐AUC, with oral ulcers, PT, ALT, albumin, and anti‐DNA also producing measurable declines, confirming their test‐time stability." (PMID 41583997, 2026). "In RF model using the embedded impurity‐based method, arthritis emerged as the most influential feature, followed by albumin, PT, oral ulcers, genital ulcers, and anti‐DNA." (PMID 41583997, 2026). "Clinically, the study’s results show how a limited number of straightforward, everyday characteristics—like arthritis, oral ulcers, albumin, and anti‐dsDNA antibodies—can help doctors identify BD earlier, especially when the symptoms are vague or overlap." (PMID 41583997, 2026). "Convergence of evidence across both models (RF and XGBoost) and all interpretability methods (embedded, permutation, and SHAP) highlights arthritis, oral ulcers, albumin, and anti‐DNA as the most robust and clinically meaningful features." (PMID 41583997, 2026). "The identification of common features across all approaches highlighted arthritis, followed by oral ulcers, albumin, and anti‐DNA." (PMID 41583997, 2026). "If we were to expand the set of most important features beyond the four basic ones (arthritis, oral ulcers, albumin, and anti‐DNA), the important candidates would be PT, ALT, CRP, creatinine, and ESR." (PMID 41583997, 2026). "Our findings highlight arthritis, followed by oral ulcers, albumin, and anti‐DNA, which significantly impact the model as highly relevant features, alongside several others such as PT, ALT, CRP, creatinine, and ESR." (PMID 41583997, 2026). "The SHAP analyses confirmed that arthritis had the strongest predictive effect, while albumin, oral ulcers, PT, and anti‐DNA followed with consistent, clinically plausible contributions." (PMID 41583997, 2026). "The models exhibited poorer performance when arthritis, oral ulcers, albumin, and anti‐DNA were omitted, reinforcing their importance in predictive modeling." (PMID 41583997, 2026). "The permutation analysis showed that test performance was most sensitive to arthritis and oral ulcers, while albumin, PT, and anti‐DNA also contributed to performance drops." (PMID 41583997, 2026).